EGFR (epidermal growth factor receptor)
Diseases named in the same sentence as EGFR in open-access papers (continued):
Sharing a sentence is not in itself a finding about the gene and the disease.
breast carcinoma (continued). "However, studies involving xenoestrogens have tested them in the absence of activators of the human epidermal growth factor receptor (HER) family of receptor tyrosine kinases (Wróbel and Gregoraszczuk 2013, 2014), a second signaling pathway implicated in breast cancer." (PMID 26502914, 2016). "In the resistant cells, but not in MCF-7, a slight increase in EGFR levels was also seen, which may reflect a stress response, especially in the resistant cell lines, since estrogen induces apoptosis in breast cancer cells adapted to long-term estrogen deprivation." (PMID 26849233, 2016). "In addition to CD24, FAK, EGFR, and Survivin, BrCa serum EVs have been found to contain the disintegrin and metalloprotease ADAM10, as well as the tetraspanin CD9, with the latter being a known functional integrin binding partner in breast cancer cells and a molecular marker of EVs." (PMID 26601108, 2015). "Altogether, the ability of EGFR and IGF-IR ligands as well as hypoxia to regulate GPER expression and function may be included among the molecular mechanisms leading to cell proliferation, migration, tumor angiogenesis that are mainly involved in breast cancer progression." (PMID 24834064, 2014). "However, the off-target activity of lapatinib in inducing EGFR expression without tyrosine kinase activity was demonstrated to render HER2-negative breast cancer cells more metastatic, suggesting a limitation to the therapeutic effectiveness of this dual inhibitor in HER2-heterogeneous tumors." (PMID 24707474, 2014). "In the cell proliferation and malignancy of MCF7 and SUM149 breast cancer cells, Src-dependent (i.e., dasatinib-sensitive) Y845 phosphorylation (i.e., Y845F mutation-sensitive) signaling was shown to require the activity of p38 MAPK, but not the activity of the EGFR/kinase ERK/MAPK, as well as Akt." (PMID 23702846, 2013). "Our estimation of positivity of breast cancers for our panel may have been conservative since we have been very stringent in calling expression positive, explaining why our rates of expression for GLUT1, CAIX, EGFR, MET, TfR, CAXII, and Mammaglobin are on the lower side compared to the literature." (PMID 22695343, 2012). "Thus, combining drugs that inhibit function of EGFR/HER2 with dual PI3K/mTOR and MEK pathway inhibitors in order to abolish compensatory mechanisms may eliminate cancer cell survival and perhaps improve therapeutic effects in HER2-positive breast cancers." (PMID 21961653, 2011). "Thus, we analysed the proteins of the HER-family (EGFR, p-EGFR, HER2, p-HER2, HER3, p-HER3, HER4) together with other proteins that are known to play important roles in general tumour progression (Akt, p-Akt, Erk, pErk), especially in breast cancer (uPA, PAI-1)." (PMID 21966358, 2011). "The most widely used panel is based on the expression of cytokeratin 5/6 (CK5/6) and/or the epidermal growth factor receptor (EGFR) in tumors that are triple-negative; however, no uniform consensus exists as to what is the optimal immunnohistochemical panel to identify basal-like breast cancer." (PMID 20979652, 2010). "The present study has demonstrated for the first time that breast cancer cell invasion can be enhanced by the ability of TNK2 to maintain EGFR cell surface expression and may provide the impetus for exploration of TNK2 as an alternative drug target for the treatment of EGFR-dependent cancers." (PMID 18435854, 2008). "Surprisingly, although this mAb displays insufficient effect against EGFR-overexpressing breast cancer, it has yielded positive clinical results against head and neck cancers overexpressing the EGFR and has demonstrated activity in colon cancer regardless of tumor EGFR expression." (PMID 18991714, 2008). "In addition to this, it was recently shown that the EGF-induced cell migration of EGFR/c-erbB-2-positive breast cancer cells, but not of solely EGFR-positive breast cancer cells, could be blocked with moderate concentrations of the PLC-γ1 inhibitor U73122." (PMID 14710234, 2004).
breast carcinoma (continued). "Although TNBC does not have the most common receptors expressed in breast cancers, it has some receptors, including EGFR (epidermal growth factor receptor) at 45–70%, PD-L1, CTLA-4, and PD-1." (PMID 40284424, 2025). "Amplifications of RTKs such as EGFR (epidermal growth factor receptor) and FGFR1 (fibroblast growth factor receptor 1) are frequently observed in breast cancers that do not respond to ET." (PMID 40244377, 2025). "For example, in tumours with high EpCAM expression but low or absent EGFR expression, such as the MCF-7 breast cancer cell line, EpCAM-targeted PIT would be a more appropriate therapeutic option." (PMID 40792441, 2025). "Two were EGFR‐positive, the breast carcinoma MDA‐MB 468 and epidermoid carcinoma A431 cell lines, and one was EGFR‐negative, the melanoma cell line A2058." (PMID 40104837, 2025). "Tumor edge spiculation is associated with positive ER and PR expression, negative HER2 and Epidermal Growth Factor Receptor (EGFR) expression, and lymph node metastasis, and we believe that it is a predictor of HR+/HER2− breast cancer." (PMID 40134601, 2025). "As a result, breast cancer cells lacking STARD7 undergo cell cycle arrest and do not properly signal through both ERα and EGFR." (PMID 40443279, 2025). "Salivary gland cancer cells (HSY, A253), and breast cancer cells (MCF7, negative control) were investigated for epidermal growth factor receptor (EGFR) expression using Western blotting analysis and immunocytochemistry (ICC)." (PMID 38542206, 2024). "Our results showed that stimulation of breast cancer cells with BEC (hCMEC/D3)-conditioned media but not control media (MEM or EC M), stimulated EGFR phosphorylation to levels similar to those of EGF stimulation." (PMID 38762624, 2024). "NT2.5-LM lung metastases are ERBB2-positive, express similarly low levels of AE1/3 and EGFR, and are similarly negative for CK5 and CK6, when compared to NT2.5 mammary tumors." (PMID 38717519, 2024). "Basal-like breast cancers show negative ER, PR, and HER2 receptor expression and express epidermal growth factor receptor (EGFR)." (PMID 36678877, 2023). "In HER2+ breast carcinoma, it has been demonstrated that HER2 (unlike EGFR) suppresses cGAS-STING signaling, hindering the cancer cells from producing cytokines, entering senescence, and undergoing apoptosis." (PMID 38139802, 2023). "In contrast to its intrinsic non-proteolytic effect on EGFR activation and cell proliferation in 3D Matrigel, the enzymatic activity of MT4-MMP was still required for the early angiogenic switch during breast cancer progression." (PMID 37373092, 2023). "Some breast cancer cell lines, mainly basal-like but also luminal and HER2-positive, have negative feedback from ERK to EGFR." (PMID 36358725, 2022). "Additionally, mutations and abnormal amplifications of many genes, such as breast cancer associated genes 1 and 2 (BRCA1/2), human epidermal growth factor receptor 2 (HER2), and epidermal growth factor receptor (EGFR) also play an important role in the occurrence and development of BC." (PMID 35978348, 2022). "It was demonstrated that administration of erlotinib, an EGFR inhibitor, prevented growth but did not eliminate BRCA1-related breast cancers." (PMID 35813830, 2022). "The phosphorylation of Tyr1068 in EGFR and Tyr1221/1222 in HER2 was detected in a HER2-positive breast cancer cell line, SKBR-3 cells, without the addition of any ligands of the HER family." (PMID 34187934, 2021). "Genome-wide proteomics of breast cancer cell lines, including SKBR3, reported hBCATc to correlate with higher levels of epidermal growth factor receptor (EGFR) expression, which is upregulated in TNBC, but not in HER2-positive breast cancer." (PMID 33367952, 2021).
breast carcinoma (continued). "Gene set enrichment analysis found upregulation of genes resistant to the Epidermal Growth Factor Receptor (EGFR) inhibitor Gefitinib, which is an alternative to hormonal therapy in Her2+ breast cancer tumours, but is not efficient in triple negative tumours." (PMID 33845831, 2021). "Therapeutic mAbs targeting EGFR (cetuximab) and VEGFR2 (ramucirumab) are approved by FDA for numerous cancer indications, but none of them are approved to treat breast cancers." (PMID 33804477, 2021). "In the ERα-negative breast cancer cells (MDA-MB-468 and MDA-MB-436 cells), rapid activation of ERK1/2 (<30min) was induced by G1 treatment via GPER/EGFR/ERK signaling, leading to cell proliferation and cell migration." (PMID 33799631, 2021). "In a HER2/EGFR-double positive breast cancer cell line, SKBR-3, the overexpression of Myc-tagged or non-tagged CNKSR1 increased the phosphorylation of both EGFR and HER2, as well as cell proliferation." (PMID 34187934, 2021). "SERPINE1 promotes breast cancer cell metastasis and glycolytic metabolism in triple-negative breast cancer (TNBC) and participates in EGFR signaling." (PMID 33509226, 2021). "They convincingly showed that they detected clinically relevant GCN alterations (i.e., ERBB2, EGFR, MET) for n = 14 breast cancer samples using the matched normal samples or a normal reference pool." (PMID 34638507, 2021). "Basal-like breast cancer is differentiated from other TNBC (ER, PR, and HER-2 negative) by expressing cytokeratin 5/6 and/or EGFR." (PMID 34458041, 2021). "Curcumin was also found to reduce EGFR activation and EGF-induced phosphorylation of ERK1/2 as well as JNK activity in breast cancer cells however, there was a lack of inhibition of p38." (PMID 34867402, 2021). "Troglitazone enhanced uptake of glucose in several breast cancer cell lines, but changes in GLUT levels do not seem to play a role in this effect, that rather appears to involve MAPK, AMPK, and EGFR." (PMID 31936350, 2020). "To investigate a role for HUNK regulation of EGFR in breast cancer, we used shRNA to target HUNK in human breast cancer cell lines that have high EGFR expression, without altering PKC activity." (PMID 31597954, 2020). "Quick literature search revealed that PTGS2, EGFR, ABCB1, and IL6 high expression rather than low expression was correlated with breast cancer growth." (PMID 32577155, 2020). "In basal-like breast cancers, the absence of the protein ALIX was shown to correlate with EGFR activation, impairing exosome biogenesis." (PMID 32923684, 2020). "One study even shows that luminal A/B breast cancer patients with high IGF-IRα and negative EGFR expression have better prognosis than the rest." (PMID 32493414, 2020). "On the other hand, EGFR is downregulated on the surface of EVs in response to TKI in cell lines which are not dependent on EGFR signalling, such as luminal breast cancer cell line MCF-7." (PMID 33302515, 2020). "By immunohistochemistry, basal-like breast carcinomas are triple negative, that is negative for ER, PR hormone receptors and HER2, while positive for basal cytokeratins 5/6, 14, 17 and EGFR." (PMID 33218360, 2020). "An in vitro study with three breast cancer cell lines showed that Epidermal Growth Factor (EGF) stimulated glucose uptake in EGFR-positive T-47D and MDA-MB-468 cells, but not in the weakly EGFR-positive MCF-7 cells." (PMID 31936350, 2020). "In this study, we adopted the widely accepted definition in which CK5/6- and/or EGFR-positive breast cancers are classified as BLBC while CK5/6- and EGFR-negative breast cancers are defined as non-basal-like breast cancer (NBLBC)." (PMID 33552956, 2020). "This strategy is unlikely to be effective in breast cancer due to downstream, non-canonical activation of GLI by other pathways such as the PIK3/AKT, EGFR, TGF-β and NF-κB pathways." (PMID 31394751, 2019).
breast carcinoma (continued). "Based on IHC subtyping (CK5/6, EGFR expression) we further segmented TNBC into basal like breast cancer (BLBC, CK5/6+, and/or EGFR+) and non-BLBC (CK5/6− EGFR−)." (PMID 31482136, 2019). "TNBC is further subclassified as basal-like breast cancer (BLBC, ER-/PR-/HER2-/CK5/6+ or epidermal growth factor receptor [EGFR] +) and quintuple-negative breast cancer (ER-/PR-/HER2-/CK5/6-/EGFR-) and accounts for 15–25% of all breast cancer cases." (PMID 31562808, 2019). "A dual inhibitor of EGFR/HER2 tyrosine kinase, lapatinib, has shown significant clinical benefits in advanced HER2-positive breast cancer patients, but the response is not durable." (PMID 31569723, 2019). "The same inverse relationship was found when examining EGFR expression in colon adenocarcinoma (COAD) and a cohort of cancer cell lines across several tissue types, but not in breast cancer (BRCA) or glioblastoma (GBB)." (PMID 31857847, 2019). "In breast cancer tissues, cells with KDM5A gene amplification were found to be more resistant to erlotinib, an inhibitor of the tyrosine kinase epidermal growth factor receptor (EGFR), when compared to cells without the same amplification." (PMID 35582714, 2019). "We had previously demonstrated that MUC1 expression drives EGFR-dependent breast cancer (in the WAP-TGFα transgenic mouse model), including >60% reduction of EGFR-driven tumor formation in the absence of MUC1." (PMID 29464085, 2018). "TNBC or basal-like breast cancer is known to be negative for HER2, shown to express EGFR in 40% of the patients, of those 18% of patients are reported to have amplified EGFR gene." (PMID 29455658, 2018). "Although our results highlight the clinical significance of targeting both the EGFR and COX-2 pathways in patients with IBC, we recognize that combination treatment of EGFR and COX-2 inhibitors in breast cancer has not been clinically successful." (PMID 28978083, 2017). "In the absence of serum or growth factors, EGFR overexpression does not appear to constitutively activate AKT, however ERBB2 overexpression has been shown to do so in breast cancer cells." (PMID 28513565, 2017). "Consistently, our data also showed that HER2, but not HER3, is involved in the heterodimerization with EGFR and in the regulation of EGF‐induced Akt signaling in HER2‐positive breast cancer cells." (PMID 28632938, 2017). "In particular, activation of IGF-IR, but not EGFR, in MCF-7 breast cancer cells results in the reduction of specific matrix metalloproteinases and their inhibitors." (PMID 28079144, 2017). "Unlike SKOV3 and A498, levels of c-MET and EGFR were not lowered by NRF2 knockdown in colorectal carcinoma HT29 and breast carcinoma MDA-MB231 cells." (PMID 29291022, 2017). "In sharp contrast with ER negative cell line, neither transactivation of EGFR nor stimulation of invasiveness was observed when ER positive MCF-7 and T47D breast cancer cells were treated with KP-10." (PMID 27101408, 2016). "Gefitinib successfully inhibited EGFR activation in SK-Br-3, MDA-MB-261, and MDA-MB-468 breast cancer cells, although p42/p44-MAPK and AKT phosphorylation was not reduced in MDA-MB-468 compared to the other cells." (PMID 26828526, 2016). "Mutations that sensitize tumors to targeted therapies, such as that found in EGFR, have so far not been identified for HER2 in the breast cancer setting." (PMID 27618787, 2016). "In this study, we show that the non-receptor tyrosine kinase PYK2 is a key effector of EGFR and HER2 signaling in human breast carcinoma." (PMID 26084289, 2015). "It has also been shown that the non-metabolism function of EGFR activates PKM2 in β-catenin transactivation and subsequent cell proliferation and tumorigenesis in GBM, prostate and breast cancer cell lines." (PMID 26147004, 2015). "Although the rate of EGFR expression is high in breast cancer, especially in TNBC, EGFR inhibitors do not have an ideal curative effect in breast cancer." (PMID 25429827, 2015).
breast carcinoma (continued). "TNBC is further subclassified as basal-like breast cancer (BLBC, ER-/PR-/HER2-/CK5/6+or epidermal growth factor receptor [EGFR] +) and quintuple-negative breast cancer (QNBC, ER-/PR-/HER2-/CK5/6-/EGFR-) and accounts for 15–25% of all breast cancer cases." (PMID 26313651, 2015). "Over a period of 24 hr, 10 μM NSC624205 killed MDA-MB-468 and SKBR3 cells, which overexpress EGFR and HER2 respectively, but had little effect on the basal-like/triple-negative MDA-MB-231 breast cancer cell line, which does not overexpress either EGFR or HER2." (PMID 25865227, 2015). "Our study found that DF extract alone had no significant growth inhibitory effect on various EGFR/ERBB2-amplified gastroesophageal and breast cancer cell lines in vitro." (PMID 24587811, 2014). "Overall, in dose-dependent drug sensitivity test, DF, as a single agent, did not significantly inhibit the growth of EGFR/ERBB2-amplified gastroesophageal and breast cancer cell lines even at supra-pharmacological doses." (PMID 24587811, 2014). "In general, there is increased phosphorylation of EGFR, AKT, S6 and 4EBP1 in breast cancer cell lines compared with immortalized non-transformed human mammary epithelial cells (HMEC-hTERT), as well as a significant decrease in AMPK phosphorylation at Thr172." (PMID 25361177, 2014). "Approximately, 15–20% of all breast carcinomas are included in the subgroup of triple-negative breast cancer (TNBC) that are characterized by the lack of ERα, progesterone receptor (PR), and EGFR 2 (Her-2)." (PMID 24834064, 2014). "Expression of EGFR, HER2, CAIX, and GLUT1 was not significantly different between male and female breast cancer." (PMID 23308200, 2013). "In contrast to female breast cancer, expression of EGFR, GLUT1, and CAIX in male breast cancer did not correlate with any clinicopathological feature." (PMID 23308200, 2013). "To distinguish between hard-wired isoform ratios and inducible promoter switching, we applied EGF or GW2974, a dual EGFR/ErbB-2 kinase inhibitor, on MCF10A cells, on another non-tumorigenic mammary cell line, and on nine breast cancer lines." (PMID 24324612, 2013). "As the ESR1 gene is believed to have an important role in ER+ breast cancer, but not in TNBC, its strong co-expression with the central EGFR gene, specifically in TNBC compared with other clinical subtypes, is rather counter intuitive." (PMID 22343619, 2012). "MDA-MB-231 primary tumors were CK18 positive, EGFR positive, Her2 negative, demonstrating that the xenograft tumors retained the MDA-MB-231 cell line expression pattern of key breast cancer markers." (PMID 23118918, 2012). "After treatment with nicotine at different time points, a cell lysate (without the nucleus) was prepared from human breast cancer MCF10A or MDA-MB-231 cells and the expression of EGFR was then tested by immunoblotting." (PMID 22085699, 2011). "Since epidermal growth factor receptor (EGFR), like S100A7, is often expressed in estrogen receptor-alpha-negative (ERα-) breast cancer, we set out to investigate the role of Jab1 in mediating EGFR signaling, another facet of the ERα- phenotype." (PMID 18534028, 2008). "EGFR is not always expressed in HER2-amplified breast cancers and HER2 is fully capable of transforming EGFR-negative cell models." (PMID 17667926, 2007). "Several of these regions contain genes known to be amplified in breast cancer, including ERBB2, EGFR and MYC, while others include genes not previously implicated in breast cancer, including PTK2." (PMID 16457699, 2005). "The target cells consisted of two breast cancer cellular lines, MDA-MB468 and SK-BR3, which were analyzed in terms of differential target molecule (EGFR) expression, as well as the presence of non-specific (MICA/B) and specific (CD1d) activating and inhibitory molecules (Fas)." (PMID 40002679, 2025).